DCN (decorin)
Diseases named in the same sentence as DCN in open-access papers (continued):
Sharing a sentence is not in itself a finding about the gene and the disease.
tumor (continued). "In accordance, low decorin levels have been associated with large tumor size, poorer survival and greater risk of early recurrence (especially when combined with high EGFR expression) in lymph node-negative invasive breast carcinomas." (PMID 33924197, 2021). "We also found that DCN expression in tumor tissues was associated with MVI, and that low DCN expression was associated with a poor prognosis." (PMID 34504839, 2021). "We found that extracellular matrix-related pathways were involved in vascular invasion of HCC and that decorin secreted by cancer-associated fibroblasts was gradually downregulated from normal to tumor tissues and more so in PVTT tissues." (PMID 34504839, 2021). "A recently uncovered implication of decorin in regulating mitophagy has been reported, which linked decorin directly to affecting the catabolic process of mitophagy within the tumor proper." (PMID 34917515, 2021). "Univariate analysis revealed that various characteristics, including age (<60 years), Ishak grade (≥6), incomplete tumor capsule, and low tumor DCN expression, were risk factors for MVI." (PMID 34504839, 2021). "In support of this, decorin acts as a tumor suppressor in many cancer types, while its loss precipitates cancer progression." (PMID 33330449, 2020). "Early genetic studies have demonstrated that deficiency of DCN is permissive for tumour development." (PMID 29435195, 2018). "Taken together, decorin loss facilitates tumour growth and progression and its markedly reduced expression in follicular thyroid tumours warrants further investigations." (PMID 27025787, 2016). "These decorin-dependent signal transduction systems are implicated in mitogenic and oncogenic functions connected with cancer cell adhesion, invasion, tumor angiogenesis and metastasis." (PMID 25526025, 2014). "The cellular and molecular functions these gene subsets represent are highly consistent for the ascribed properties of decorin functioning in a tumor repressive capacity as these classifications are associated with tumor suppressive activity." (PMID 23029096, 2012). "Others have previously shown that matrix proteoglycans lumican and decorin are abundant components of breast tissue stroma and that altered expression of lumican and decorin is associated with tumor progression and outcome." (PMID 21791066, 2011). "Adenoviral overexpression of decorin caused primary tumor retardation of 70%, in addition to greatly reducing the observation of metastasis." (PMID 20092659, 2010). "When comparing the expression difference between normal and tumour samples, we found significant underexpression of the DCN gene in the group of tumours with activating KRAS mutations in comparison with tumours without these mutations (p < 0.05)." (PMID 19678923, 2009). "Low levels of decorin protein in invasive breast cancers have also been associated with larger tumor size, shortened duration to progression and poor outcome." (PMID 19036156, 2008). "In addition, DCN positive B cells interacting with tumour cells were also associated with shorter OS." (PMID 41392017, 2026). "Decorin’s multiple interactions with growth factors, their receptors and associated down-stream pathways highlights its multifaceted roles in growth inhibition, metastasis and angiogenesis of tumours." (PMID 41300368, 2025). "More recently, decorin has been implicated in the regulation of tumour lymphangiogenesis." (PMID 41463344, 2025). "There are two possible hypotheses for how variation in VEGF and decorin in the tumour could influence the risk for tumour recurrence." (PMID 37104411, 2023).
tumor (continued). "Interestingly, some of the genes involved in collagen organization, including DCN, which has been associated with tumor suppressive activities, or COL3A1 were downregulated upon co-culture with organoids in both NFs and CAFs." (PMID 36868311, 2023). "As seen with VEGF, decorin immunostaining was also associated with tumour necrosis." (PMID 37104411, 2023). "This may indicate a role of decorin in mediating the regulation of the expression of adhesion metastasis-associated molecules (E-cadherin and MMPs) and inhibiting tumor metastasis." (PMID 35777025, 2022). "Interestingly, loss of decorin within the ECM of ductal carcinoma in situ due to ECM remodeling is a marker for tumor progression and correlates with more aggressive disease." (PMID 35435599, 2022). "It is tempting to speculate that loss of decorin during tumor progression may increase TGFβ1 bioavailability in the tumor microenvironment." (PMID 35435599, 2022). "Moreover, multivariate logistic models showed that low tumor DCN expression was an independent risk factor for MVI." (PMID 34504839, 2021). "Decorin evokes sustained autophagy by transcriptional activation of Peg3 (Paternally expressed gene 3), an imprinted gene expressed exclusively from the paternal allele, and that is often silenced in several tumor types by promoter hypomethylation." (PMID 34917515, 2021). "We cannot exclude the possibility that stroma-derived DCN could also contribute to tumor suppressor function in IBC, because others have linked reduced levels of stromal DCN with more aggressive disease." (PMID 33452400, 2021). "In addition, DCN was gradually downregulated from normal fibroblasts to primary tumor-associated fibroblasts and further in PVTT-associated fibroblasts." (PMID 34504839, 2021). "Importantly, an emerging body of evidence points to the vital implications of the SLRPs decorin and biglycan in several hallmarks of cancer and regulating tumor-associated pathways, such apoptosis, proliferation, angiogenesis, inflammation, and autophagy." (PMID 34917515, 2021). "Distinguished with VCAN and THBS2, though DCN was associated with the extracellular matrix, it could antagonize many tyrosine kinase receptors to inhibit tumor development and progression." (PMID 33200655, 2020). "Conversely, the overexpression of lumican in melanoma cells inhibited tumor formation in an animal model, whereas low expression levels of lumican and decorin are associated with a poorer patient survival in breast tumors and spindle cell carcinomas, respectively." (PMID 33202923, 2020). "Studies have shown that deficiency of DCN is permissive for tumour development, whereas overexpression of DCN could block the cell cycle and decrease the invasive ability of cancer cells." (PMID 30922331, 2019). "Decorin deficient mice showed increased rate of tumor formation and poor cell differentiation." (PMID 29568375, 2018). "Mechanistically, PDGFRα, EGFR, IGF-IR, and macrophage-stimulating 1 receptor (MST1R) were activated in decorin-deficient mice, suggesting that decorin acts as a secreted tumor suppressor during hepatocarcinogenesis by hindering the action of another receptor tyrosine kinase." (PMID 30297672, 2018). "Nevertheless, in tumor-associated angiogenesis and in various inflammatory processes, the antiangiogenic activity is predominant, providing a potential basis for the development of decorin-based therapies." (PMID 27809279, 2016). "Our analysis of adaptive immune response during MB49 and MB49-I development and exploration of molecules secreted by both tumours showed that MB49-I has developed two mechanisms to acquire invasion properties: loss of putative tumour antigens and overexpression of decorin." (PMID 24142880, 2013). "The expression arrays revealed that decorin was down-regulated in tumor tissues, so we speculate that loss of decorin expression may contribute to the high proliferation of mammary epithelial cells." (PMID 20092659, 2010).
tumor (continued). "Another possibility suggested by the authors is that DCN is a pro-invasive molecule, which has been refuted by many studies showing its anti-invasive function in trophoblast cells, upregulation in PE-associated decidua, and tumor-suppressive function when upregulated in tumor-stroma." (PMID 34638928, 2021). "Therefore, it seems that malignant behavior and tumor progression may be correlated with the loss of endogenous decorin expression." (PMID 32477937, 2020). "In addition, we found consistency of this relationship within different areas of an individual tumor, supporting our hypothesis that DCN overexpression may be intimately linked with the high ADCL phenotype." (PMID 32908231, 2020). "In order to assess the expression of DCN in tumour cells, stroma and immune cells, SPTCs from 27 patients were stained with a 6‐plex immunofluorescent panel including DCN, CD4, CD8, CD20, CD68, and PanCK." (PMID 41392017, 2026). "Varying expression of DCN was denoted in both tumour cells, immune cells and stroma, but the prognostic significance was mainly assigned to its expression in B cells." (PMID 41392017, 2026). "CD20+DCN+ B cells interacting with tumour cells remained prognostic in multivariable Cox regression, also in adjusted analysis when applying the continuous variable." (PMID 41392017, 2026). "In particular, a higher percentage of DCN positive B cells, overall and in interaction with tumour cells, were independent predictors of shorter survival." (PMID 41392017, 2026). "An overview of the interpatient distribution of DCN positivity in tumour cells, in immune cell subsets and in the stromal compartment unveiled some, but no tangible, degree of heterogeneity." (PMID 41392017, 2026). "This study interrogated the potential clinical significance of both systemic and tumour‐specific DCN in patients with newly diagnosed PDAC participating in a prospective, observational clinical study." (PMID 41392017, 2026). "It has also been shown that decorin levels in the stroma of cancerous tumours are higher than in physiological tissues." (PMID 41463127, 2025). "DCN was identified as a tumor suppressor in HCC, and it regulates the proliferation and metastasis of HCC cells." (PMID 40693878, 2025). "Overall, the multifaceted capacity of decorin to attenuate in vivo tumor growth and metastatic spreading has long been well‐established." (PMID 40542654, 2025). "The integrin-mediated adhesion and mechanotransduction functions of decorin help decrease the development of invasive tumour cell phenotypes." (PMID 41463127, 2025). "Within tumor tissues, mRNA levels of decorin target proteins—including hepatocyte growth factor receptor (Met), VEGF-A, and β-catenin—were significantly reduced." (PMID 41445946, 2025). "The significant up-regulation of COL1A2, COL1A1 and DCN in the TME of CC illustrates the phenomenon of fibroblasts’ activation in the tumor microenvironment." (PMID 40124621, 2025). "The expression pattern between the different groups seen in the expression of CCL3 was similar to that of DCN, with the addition of tumour tissue of the severely fibrotic patients being upregulated compared to the normal SI, albeit lacking significance." (PMID 40998421, 2025). "Subgroup 3 and 7 expressed inflammatory subtypes such as CFD, PDGFRA and DCN, and the remaining tumour cells expressing inflammatory markers were named iCAF." (PMID 39789383, 2025). "Image analysis of immunohistochemical staining revealed significantly reduced collagen I and III in RdB/IL12/DCN or RdB/IL12/DCN + αPD-1-treated tumor tissue compared to PBS- or αPD-1-treated tumor tissues." (PMID 40335925, 2025). "Versican (VCAN) and LAMC1, which are strongly associated with tumor progression and increased metastasis risk, were identified only in CRLM-SD, whereas TIMP3 and decorin, which are linked to an opposing effect in cancer, were found exclusively in CRLM-CA." (PMID 40617497, 2025).
tumor (continued). "Further exploration is needed to understand how DCN inhibits tumor proliferation in OSCC, particularly through pathways involving TGF-β." (PMID 40109852, 2025). "Based on a quantitative comparison between tumor and NAT ECM, we observed a substantial loss of PROs (i.e., DCN, OGN, LUM, and HAPLN1)." (PMID 40032993, 2025). "The combination of decreased ECM signalling and restricted RTK activation through elevated decorin levels leads to reduced tumour cell growth and adhesion and enhanced immune cell entry into the less rigid microenvironment." (PMID 41463127, 2025). "Due to these strong functions in cancer behaviour, it is not surprising that there has been an attempt to trace the dynamics of expression of decorin in healthy and tumoural mammary samples." (PMID 41463344, 2025). "SMA, PDGFRB, SDF1, POSTN, and DCN were also found in fibroblast-like cells within the connective tissue septa separating tumor cell nests, with POSTN and DCN occasionally present at the bone surface (data not shown)." (PMID 40841830, 2025). "In contrast, tumors in the RdB/IL12/DCN-only treated group showed significant growth, with the average tumor volume reaching 3,124 mm3 by day 31 post-rechallenge." (PMID 40335925, 2025). "DCN plays a crucial role in numerous cellular functions, such as collagen fibrillogenesis, wound healing, angiostasis, tumour development, and autophagy." (PMID 40001470, 2025). "Another example of such regulation is a chimeric promoter composed of the Ki67 promoter positioned upstream of an HRE sequence to drive E1A expression; the resulting OAd HRE-Ki67-Decorin virus suppressed tumor growth in subcutaneous RCC models." (PMID 41445946, 2025). "DCN can inhibit tumor cell proliferation, invasion, and metastasis by upregulating the expression of IL-8 and MMP-7." (PMID 40109852, 2025). "In agreement with this, a recent PG gene-signature study in BC confirmed that high stromal decorin expression correlates with improved survival and reduced metastatic potential, reinforcing its prognostic value as a stromal-derived tumour suppressor." (PMID 41463344, 2025). "For instance, small leucine-rich PG, decorin, affects collagen fibrillogenesis and suppresses angiogenesis, thus limiting tumour growth." (PMID 41463344, 2025). "The presence of decorin in tumour stroma is commonly seen as a protective factor which indicates a less aggressive tumour environment with reduced fibrosis." (PMID 41463127, 2025). "Upon binding to various receptors, DCN regulates crucial processes essential for tumor growth, invasion, and progression." (PMID 40109852, 2025). "The expression of DCN was significantly upregulated in the mesenteric mass compared to both the normal SI and primary tumour tissue of patients in each fibrotic category." (PMID 40998421, 2025). "Decorin regulates tumor growth by binding to TGF-β, which inhibits its activity, and to the EGF receptor, which acts as an antagonist." (PMID 40141107, 2025). "Most of the previous data surrounding Decorin expression suggests a tumor‐suppressive role; however, in CXPA it appears to have the opposite effect." (PMID 39155517, 2025). "The increased decorin levels indicate positive changes in the TME which create an environment that becomes less conducive to tumour expansion and metastasis." (PMID 41463127, 2025). "DCN exerts tumor-suppressive effects by inhibiting tumor proliferation, regulating angiogenesis, and inducing inflammation and autophagy." (PMID 40109852, 2025). "The elevated decorin levels indicate stronger stromal structure maintenance and tumour-controlling environmental changes that match decorin’s proven ability to block TGF-β signalling, receptor tyrosine kinase activity and angiogenesis in a tumour stroma." (PMID 41463127, 2025).
tumor (continued). "Mechanistically, RBM15 promotes CC progression by installing m6A modification on the tumor suppressor DCN mRNA, thereby reducing DCN expression; conversely, RBM15 silencing enhances DCN expression, while DCN depletion reverses this tumor-suppressive effect." (PMID 41403702, 2025). "DCN, functioning as a signaling molecule, can regulate cellular autophagy, thereby inhibiting tumor metastasis and proliferation." (PMID 40109852, 2025). "Meanwhile, Domain 4 expressed tumor-suppressive genes like DCN, LUM, BGN, and COL1A2, suggesting a protective microenvironment." (PMID 40838787, 2025). "Do the functions of tumor suppression, angiogenesis, cell autophagy, and others mediated by DCN act independently or synergistically?" (PMID 40109852, 2025). "For instance, does DCN contribute to the process of oral mucosal carcinogenesis by inducing endothelial cell autophagy and tumor cell autophagy?" (PMID 40109852, 2025). "Mechanistically, loss of Klk1 promoted extracellular matrix (ECM) remodeling by upregulating Mmp2, Mmp9, Fap, decorin, and β‐catenin, thereby promoting epithelial‐mesenchymal transition and tumor progression." (PMID 40859429, 2025). "DCN is a crucial component of the extracellular matrix, playing a significant role in tumor development." (PMID 40109852, 2025). "To validate this finding, we assessed the correlation between CCL19 and the fibroblast marker DCN, which reached 0.45 in the intra-tumor immune infiltration spots." (PMID 39505867, 2024). "Given decorin’s tumor suppressor function, this proteoglycan is a promising therapeutic target for cancer." (PMID 38675493, 2024). "Decorin, a proteoglycan associated with ECM that functions as a tumor suppressor, binds to the mature forms of all three TGF-β isoforms, thereby blocking TGF-β signaling." (PMID 38675493, 2024). "It has been well-known that decorin is a natural inhibitor of TGFβ signaling, which plays an important role in regulating tumor proliferation, apoptosis, angiogenesis, epithelial-mesenchymal transition (EMT) and so on." (PMID 39306655, 2024). "And, we have previously reported that decorin was significantly down-regulated, while Met was increased obviously in tumor tissues of CRC patients." (PMID 39306655, 2024). "In summary, our results highlight DCN’s pivotal role in tumor suppression, particularly in CMS2 regions with elevated invasiveness potential." (PMID 38200223, 2024). "Decorin (DCN) exhibits the capability to inhibit tumor cell growth and metastasis, induce tumor cell apoptosis, and degrade tumor stroma." (PMID 39482550, 2024). "Our previous studies have reported that oncolytic adenovirus expressing decorin, a natural inhibitor of transforming growth factor β (TGFβ) signaling, produced obvious anti-tumor responses in various animal models." (PMID 39306655, 2024). "Our results suggested that decorin (DCN), a proteoglycan secreted by stromal cells, triggers a protective pathway inhibiting tumor progression in the CMS2 subtype." (PMID 38200223, 2024). "Results showed that both rAd.DCN + NK group 1 and group 2 significantly inhibited tumor growth compared to the control group." (PMID 39482550, 2024). "Overall, rAd.DCN promoted the proliferation and persistence of NK cells and partially reversed the immunosuppressive tumor microenvironment, enhancing NK cell tumor-killing efficacy." (PMID 39482550, 2024). "In this study, we demonstrated that intratumorally injected adenovirus remained detectable until day 28 and efficiently produced Decorin in tumor tissue." (PMID 39482550, 2024). "The new data demonstrate that DKK1 is highly expressed in the tumor area of immune-exclusion samples, with DCN+CCL19+ fibroblasts excluded from the tumor core." (PMID 39505867, 2024). "Regarding the proteoglycan metabolism, this study found significant decreased levels of UDP-GlcDH in tumor samples, as well as of lumican, decorin, and mimecan." (PMID 39195201, 2024).